ITGA2 (integrin subunit alpha 2)
Diseases named in the same sentence as ITGA2 in open-access papers (continued):
Sharing a sentence is not in itself a finding about the gene and the disease.
pancreatic cancer (continued). "Oncomine analysis of cancer vs. normal tissue confirmed that COL12A1, FN1, ITGA2, LAMB3, LAMC2, THBS2, and VCAN were significantly overexpressed in pancreatic cancer from different datasets." (PMID 34007003, 2021). "Histopathological evidence shows that ITGA2, LAMB3, and LAMC2 are expressed exclusively from pancreatic cancer cells." (PMID 34007003, 2021). "THBS2 and VCAN were expressed in both stromal and pancreatic cancer cells, whereas ITGA2, LAMB3, and LAMC2 were solely expressed by pancreatic cancer cells." (PMID 34007003, 2021). "Therefore, ITGA2 could promote tumor growth in pancreatic cancer in vivo." (PMID 31818309, 2019). "Our list identified several genes that have been found to be activated in pancreatic cancer such as MET, MAP4K4, and ITGA2." (PMID 30092011, 2018). "Additionally, ITGA2 inhibits the activation of the TGF-β pathway via the TFCP2–SMAD2 axis, thereby promoting progression in pancreatic cancer." (PMID 40940943, 2025). "The objective of this study is to assess the presence of ITGA2, EMT and PD-L1 in pancreatic cancer." (PMID 37881431, 2023). "To investigate whether ITGA2 regulates immune function in pancreatic cancer, we conducted ITGA2, CD4, and CD8 assays on postoperative specimens from 62 patients with pancreatic cancer." (PMID 37881431, 2023). "Additionally, we aimed to investigate the relationship between ITGA2 and EMT/PD-L1 in pancreatic cancer cells." (PMID 37881431, 2023). "Further experimental verification is needed to confirm the immunosuppressive role of ITGA2 in the immune regulation of pancreatic cancer microenvironment, as there is a negative correlation between ITGA2 and CD4 and CD8." (PMID 37881431, 2023). "In addition, the ITGA2 silencing and TGF-β expression also promoted the apoptosis of pancreatic cancer cells and their combination increased the apoptosis rate of tumor cells." (PMID 35193647, 2022). "Therefore, SMAD2 upregulation mediated the anti-tumor effect of ITGA2 silencing in pancreatic cancer, which represents treatment by inducing the SMAD2 expression as a novel therapeutic strategy for pancreatic cancer." (PMID 35193647, 2022). "The LC-MS/MS analysis showed that the TFCP2 could interact with ITGA2; this interaction was identified by detecting the peptides of TFCP2, which had been verified using immunoprecipitation assays in the pancreatic cancer cells." (PMID 35193647, 2022). "ITGA2 inhibited the SMAD2 expression by interacting with TFCP2 but did not change the TFCP2 expression in the pancreatic cancer cells." (PMID 35193647, 2022). "Moreover, in the Pei pancreas dataset, COL12A1, FN1, ITGA2, LAMB3, LAMC2, THBS2, and VCAN mRNA expression levels were higher in pancreatic cancer tissue than in normal pancreatic tissue samples." (PMID 34007003, 2021). "Since the differential expression of ITGA2 was more significant in pancreatic cancer compared with non-tumor tissue, we paid more attention to exploring the biological role of ITGA2 in PDAC." (PMID 31818309, 2019). "The IHC staining score was evaluated and the results showed that ITGA2 proteins increased profoundly in pancreatic cancer tissues compared with non-tumor pancreatic tissues b,c." (PMID 31818309, 2019). "In this study, ITGA2+ cells density were found to be significantly correlated with CA-199 (P= 0.004), CEA (P=0.03), TNM stage (P= 0.037), lymph node metastasis (P= 0.001) and local invasion (P= 0.02), indicating its importance in the diagnosis and growth of pancreatic cancer." (PMID 37881431, 2023). "Similarly, the overexpression of ITGA2 could inhibit the expression of SMAD2 and phosphorylation of SMAD2/3 in the pancreatic cancer cell." (PMID 35193647, 2022). "Moreover, our study reveals the potential mechanism that hsa-miR-15a-5p regulates COL1A2, ITGA2, and LAMA3 so that monocytes and M1 macrophages are activated, which may have great effects on pancreatic cancer prognosis." (PMID 35899199, 2022).
pancreatic cancer (continued). "However, the reason for the high expression level of ITGA2 in pancreatic cancer has not been clarified." (PMID 35193647, 2022). "Therefore, ITGA2, by effectively enhancing the anti-cancer effects of TGF- β, might be a potential clinical therapeutic target for pancreatic cancer." (PMID 35193647, 2022). "Furthermore, our results also indicated that ITGA2 silencing enhanced the anti-pancreatic cancer cell proliferation effect of TGF-β treatment, and the combined treatment might represent a novel therapeutic strategy for pancreatic cancer." (PMID 35193647, 2022). "Furthermore, the overexpression of ITGA2 could significantly inhibit the mRNA level of SMAD2 in pancreatic cancer cells, but not those of the SMAD3 or SMAD4." (PMID 35193647, 2022). "In order to investigate the biological effects of ITGA2 silencing and TGF-β expression on pancreatic cancer in-vivo, the PANC-1 cells with or without ITGA2 gene silencing were subcutaneously injected into the nude mice to induce tumorigenesis." (PMID 35193647, 2022). "It was also observed that ITGA2, LAMB3, and LAMC2 were the only proteins expressed in pancreatic cancer cells but not in stromal cells." (PMID 34007003, 2021). "The other proteins in these pathways were members of the families of interleukin (ITGA2, ITGB6), laminin (LAMC2), and collagen (COL1A1/2, COL6A3), together with cartilage oligomeric matrix protein (COMP), whose role in pancreatic cancer has not yet been clarified." (PMID 33194391, 2020).
gastric cancer (32 papers, 2016 to 2026). A primary or metastatic malignant neoplasm involving the stomach. "ITGA2 expression was validated in exosome-treated cells and in clinical gastric cancer tissues versus adjacent normal tissues using RT-qPCR and western blotting." (PMID 41627637, 2026). "ITGA2 was also markedly overexpressed in human gastric cancer tissues compared with adjacent normal mucosa." (PMID 41627637, 2026). "Chemotherapy resistance contributes to poor outcomes in gastric cancer (GC), and overexpressed ITGA2 has been observed in chemotherapy-resistant cells, suggesting a role in mediating resistance." (PMID 41008552, 2025). "ITGA2, a downstream effector molecule of the HMGA2-FOXL2 pathway, is implicated in early distant metastasis of tumor cells in gastric malignant tumors." (PMID 37881431, 2023). "The UBE2CP3 pseudogene drives gastric cancer metastasis by sponging miR-138-5p and mediating ITGA2 expression." (PMID 36348434, 2022). "The mir-135B-5p/ITGA2 signaling axis has been demonstrated to reduce the degree of EMT in gastric cancer chemotherapy trials by inhibiting the MAPK/ERK pathway, restoring gastric cancer cells’ chemotherapeutic sensitivity, and boosting mortality." (PMID 35897925, 2022). "For instance, the ectopic expression of miR-30a suppresses the proliferation and migration and tumorigenesis of gastric cancer cells by directly inhibiting ITGA2.More notably, the immunomodulatory effect of miR-30a has been disclosed in several studies." (PMID 35003515, 2021). "In contrast to the expression in normal tissues, experts found that the mRNA expression of ITGA2 in gastric cancer was obviously increased." (PMID 34778054, 2021). "In other words, it’s the dysregulation of the ceRNA network “UBE2CP3/miR-138/ITGA2” that drives the malignant progression and metastasis of gastric carcinoma." (PMID 34274947, 2021). "The expression of ITGA2 was found to be upregulated in several types of tumors (e.g., gastric cancer, prostate cancer, and non-small cell lung cancer) and it is closely associated with tumor invasion." (PMID 30996239, 2019). "Recently, it has been reported that ITGA2 is upregulated in 375 human gastric tumor tissues and ITGA2 antibodies mediate potent cell apoptosis in human gastric cancer AGS cells through RhoA-P38 signaling pathways." (PMID 30996239, 2019). "In this report, we assessed the ITGA2 as the potential therapeutic target with the bioinformatics tools from the TCGA dataset in which composed of 375 gastric cancer tissues and 32 gastric normal tissues." (PMID 29743821, 2018). "We also discussed the down-regulation of N-WASP, PAK and LIMK, downstream of Cdc42 and Rac1, which altered actin organization and was involved in targeting ITGA2 inhibited cell migration of gastric cancer cells." (PMID 29743821, 2018). "Up-regulation of ITGA2 seems to be one of the important factors accelerating tumor progression and metastasis in various types of cancers, including gastric cancer." (PMID 29743821, 2018). "Blockade of ITGA2 dually inhibited gastric cancer cells by inducing apoptosis and inhibiting cell migration, depending on the dose and duration of exposure." (PMID 29743821, 2018). "In this study, we found that caspase-3 expression was increased in AGS gastric cancer cells after treatment with the anti-ITGA2 antibody." (PMID 29743821, 2018). "In line with this notion, blocking ITGA2 was shown to inhibit cell migration and metastasis of gastric cancer." (PMID 29743821, 2018). "In this study, our results demonstrated that ITGA2 is over-expressed in a majority of gastric cancer." (PMID 29743821, 2018). "In this study, we found that blockade of ITGA2 by a specific antibody inhibited gastric cancer cells by two mechanisms: reduced cell viability (increased apoptosis) and reduced cell migration." (PMID 29743821, 2018).
gastric cancer (continued). "To characterize the molecular mechanism by which blockade of ITGA2 induced apoptosis in gastric cancer cells, we analyzed the mRNA expression of genes that are involved in the apoptotic pathways." (PMID 29743821, 2018). "Among the hits identified in the CagA screen, 4 of them (MMP1, CEACAM6, ITGA2, C3) showed at least 2-fold increases in gastric cancer when compared to normal controls." (PMID 27421133, 2016). "The downstream targets of ITGA2 implicate multiple pro-tumorigenic signaling networks, suggesting that the exosomes-ITGA2 axis may represent a novel therapeutic target in gastric cancer progression and metastasis." (PMID 41627637, 2026). "Furthermore, the HMGA2–FOXL2 axis has been implicated in regulating metastatic processes in drug-resistant gastric cancer, suggesting a potential indirect modulation of ITGA2 function." (PMID 40940943, 2025). "Moreover, ITGA2 silencing induces apoptosis in gastric cancer and is able to restore sensitivity to paclitaxel in ovarian cancer via inhibition of AKT/FOXO1 signaling." (PMID 36765586, 2023). "The use of ITGA2 blocking antibodies inhibits migration and induces apoptosis of gastric cancer cells, while overexpression of ITGA2 stimulates PD-L1 expression by activating the STAT3 signaling cascade, leading to the more aggressive behavior of malignant pancreatic cells." (PMID 34503200, 2021). "In the research of gastric cancer, miR‐135b‐5p could target ITGA2 via ERK pathway to regulate the chemoresistance of the gastric cancer cells." (PMID 32557953, 2020). "In gastric cancer, inhibition of ITGA2 induced apoptosis and decreased cell migration." (PMID 32557953, 2020). "Furthermore, in gastric cancer, a high expression of ITGA2 was distinguished in metastatic compared to primary gastric cancer tissues and the integrin was correlated with poor prognosis." (PMID 32824235, 2020). "Similarly, ITGA2/B1 expression accelerated either experimental metastasis or tumour dissemination of melanoma and rhabdomyosarcoma, gastric cancer and colon cancer cells." (PMID 33276802, 2020). "Similar effects were also observed in ITGA2 antibody blocking studies of gastric cancer cells." (PMID 30996239, 2019). "Additionally, the ITGA2 mRNA expression levels of 38 human gastric cancer cell lines were analyzed from the Cancer Cell Line Encyclopedia (CCLE) database." (PMID 29743821, 2018). "A spectrum of ITGA2 expression was noted across the gastric cancer cell lines studied." (PMID 29743821, 2018). "One research has found that ITGA2 was overexpressed in a variety of gastric cancer patients mainly playing pro-survival roles, and the blockage of ITGA2 could induce apoptosis and inhibit cell migration in gastric cancer." (PMID 30428899, 2018). "Moreover, blocking ITGA2 by the specific antibody at lower doses also inhibited cell migration of gastric cancer cells." (PMID 29743821, 2018). "Thus, we confirmed that the AGS and SNU-1 cells display contrasting ITGA2 expressions and we used these two cell lines to further investigate the potential role of ITGA2 in gastric cancer." (PMID 29743821, 2018). "Accordingly, ITGA2 signaling inhibition may prevent metastasis of gastric cancer through down-regulating Rac 1/CDC42 signaling pathway." (PMID 29743821, 2018). "Direct application of anti-ITGA2 antibodies to treat gastric cancer may induce considerable cytotoxicity to these cells." (PMID 29743821, 2018). "Our data indicated that ITGA2 may represent a promising candidate because a majority (74%) of gastric cancers over-expressed ITGA2." (PMID 29743821, 2018). "Moreover, blockade of ITGA2 by a specific antibody dually suppresses gastric cancer by inhibiting cell migration and inducing apoptosis." (PMID 29743821, 2018). "Our findings suggest that ITGA2 is a potential therapeutic target for gastric cancer." (PMID 29743821, 2018). "Collectively, these data also support that blocking ITGA2 may be a promising method to inhibit migration of gastric cancers." (PMID 29743821, 2018).
gastric cancer (continued). "Surprisingly, we found that prolonged blockade of ITGA2 by a specific antibody at a relatively low dose (3 μg/ml) also suppresses gastric cancer cell survival, which is previously unknown." (PMID 29743821, 2018). "Blockade of ITGA2 by the antibody may induce apoptosis through RhoA-p38 MAPK signaling pathway in gastric cancer cells, consistent with previous reports that the RhoA and p38 MAPK are rapidly activated, upon cellular cholesterol depletion, to induce apoptosis." (PMID 29743821, 2018). "Thus, targeting ITGA2 may be a promising therapy to improve the survival of gastric cancer patients." (PMID 29743821, 2018). "Thus we performed transwell cell migration assay to determine whether ITGA2 blockade could inhibit migration of gastric cancer cells." (PMID 29743821, 2018). "Thus the development of targeted therapies against ITGA2 may improve survival of advanced gastric cancer patients." (PMID 29743821, 2018). "Blockade of ITGA2 by a specific antibody down-regulated the expression of N-WASP, PAK and LIMK to impede actin organization and cell migration of gastric cancer cells." (PMID 29743821, 2018). "Furthermore, we found an overexpression of ITGA2, which regulates Metastases and EMT, LAMC2 and WNT5A genes, that mediate invasion of gastric cancer cells." (PMID 34012923, 2021). "Furthermore, ITGA2 controls the MAPK pathways and EMT in gastric cancer cells, and these events closely contribute to the chemo-resistance of gastric cancer." (PMID 32899691, 2020). "In addition, ITGA2-induced chemoresistance is reversed by upregulation of miR-135b-5p, which inhibits MAPK/ERK and EMT pathways in gastric cancer cells." (PMID 32824235, 2020). "The mRNA expressions of ITGA2 were significantly higher in gastric cancers than in the normal gastric tissues (cancer expression (mean ± SD): 13.1 ± 10 vs. normal expression: 4.6 ± 3.98, p < 0.0001)." (PMID 29743821, 2018). "Statistical analysis using the paired t-test indicated a significant difference in the mRNA levels of ITGA2 between the gastric cancer and non-cancerous tissues (cancer expression: 11.1 ± 9.39 vs. normal expression: 4.9 ± 4.24, p < 0.01)." (PMID 29743821, 2018). "Similarly, overexpression of ITGA2 in esophageal squamous cell carcinoma cell lines promoted EMT and metastasis through FAK/AKT pathway and also showed chemotherapy resistance in gastric cancer, while ITGA2 knockdown restored chemosensitivity by inducing apoptosis in chemoresistant cells." (PMID 36463238, 2022). "We did not address whether JNK pathways have involved the gastric cancer cell death treated with the anti-ITGA2 antibody at the moment." (PMID 29743821, 2018). "Another research in gastric cancer revealed that HMGA2, FOXL2, and ITGA2 were increased in metastatic lymph nodes and distant metastases in gastric cancer, and suppressing the HMGA2-FOXL2-ITGA2 pathway could serve as a new strategy in further treatment in gastric cancer." (PMID 30428899, 2018).